IL6 (interleukin 6)
Diseases named in the same sentence as IL6 in open-access papers (continued):
Sharing a sentence is not in itself a finding about the gene and the disease.
liver cancer (continued). "As TDO2 expression contributed to liver cancer progression through Kyn/AhR/IL-6 signaling, we next examined the effects of combination therapy using AhR inhibitor PDM2 together with chemotherapeutic DOX or 5-FU." (PMID 34657635, 2021). "In consistent, elevated expression of IL-6 was observed in H-S tumor tissues, and poor overall survival was found in IL-6 high expression patients with liver cancer." (PMID 34657635, 2021). "In mechanism, we found that activation of AhR contributed to the upregulation of IL-6, which further promotes liver cancer development through a STAT3 and NF-kB/TIM4 dependent manner." (PMID 34657635, 2021). "The current results confirm the findings of studies identifying AKT1, CDKN2A, ERBB2, and IL6 as critical markers for metastasis of pancreatic and liver cancers." (PMID 35154607, 2021). "IL-6 is transcriptionally induced via the AhR, which was involved in the progenitor/stem cells proliferation in liver cancer." (PMID 34657635, 2021). "Enhanced expression of IL-6 was observed in most human liver cancer tissues, in which it was produced in an autocrine manner in tumor cells." (PMID 34657635, 2021). "Hepcidin expression in liver cancer tissues positively correlated with the bone morphogenetic protein-6 (BPM6)/interleukin-6 (IL6) cytokines and cytotoxic immune infiltration." (PMID 34277457, 2021). "Using liver cancer cell lines and subcutaneous mice models, we demonstrated that Kyn produced by TDO2/Trp metabolism activated AhR/IL-6 pathway in liver cancer, eventually resulting in upregulation of the NF-kB/TIM4/STAT3 signals and cancer development." (PMID 34657635, 2021). "The expression of IL-6 is very low in normal human cells, with increased serum concentration in patients with hepatitis and liver cancer." (PMID 34976809, 2021). "Our findings suggest an intricate interplay between the genes CYP2D6, HNF4A, and IL6 in AS and CA liver cancer patients." (PMID 34597305, 2021). "In the mouse liver cancer model induced by the carcinogen DEN, knock out of the GPER gene can significantly promote the occurrence of liver cancer, accompanied by immune cell infiltration, fibrosis, and the production of inflammatory factors (such as IL-6)." (PMID 35096574, 2021). "Studies have suggested that estrogen protects against liver cancer by blocking release of the growth factor Interleukin-6 (Il-6) by Kupffer cells following DEN exposure." (PMID 34068249, 2021). "Crocin displayed an anti-liver cancer potential through the inhibition of the IL-6/STAT3 signaling pathways." (PMID 34639131, 2021). "Existing studies revealed that IL-6 can upregulate Beclin-1 and induce autophagy by increasing the level of NS5ATP9 through NF-κB activation; in turn, NS5ATP9 can upregulate IL-6 levels, which subsequently further induced autophagy in liver cancer." (PMID 34895252, 2021). "The importance of IL6 in our liver cancer health disparity dataset was further validated using Cytohubba plug-in, which identified IL6 as a hub gene with the highest degree of connectivity." (PMID 34597305, 2021). "More importantly, we observed that BMP2 activated MDSCs to secrete IL6, which directly enhanced the proliferation of liver cancer cells." (PMID 32195173, 2020). "Through bone marrow transplantation experiments, deletion of IL-6, specifically in monocytes, delayed liver cancer formation in Mdr2−/− transgenic mice, suggesting that IL-6 secreted from the monocytes are directly involved in liver cancer formation." (PMID 32283687, 2020). "Our results were supported by those obtained by Zhang et al41 that Tim‐3 significantly up‐regulated the transcription and secretion of IL‐6 in liver cancer cells through NF‐κB/IL‐6/pSTAT3 axis." (PMID 32020709, 2020). "TAMs also utilize IL-6/STAT3 axis to promote expansion of liver cancer stem cells (CSCs) via autocrine IL-6 signaling." (PMID 33718121, 2020). "In our results, BMP2 signaling activated MDSCs to secrete IL6, further enhancing liver cancer cell proliferation." (PMID 32195173, 2020).
liver cancer (continued). "The MDSC population is influenced by liver cancer cells (HCCs) and augmented with liver stromal cells (HSCs), as well as IL-6 secreted from HSCs." (PMID 31614930, 2019). "On the other side, in studies using KO mice, IL-6 antagonists or estrogen analogs to prevent HCC indicate that other mechanisms must be induced in females for liver cancer protection." (PMID 31049358, 2019). "LncRNA DILC regulates liver cancer stem cells by inhibiting IL-6, which contribute to the development of RA, indicating the potential involvement of lncRNA DILC in RA." (PMID 30944206, 2019). "Among the top upregulated genes, Nogo-B attracted our attention because it was previously reported to regulate liver cancer proliferation through the IL-6/STAT3 pathway." (PMID 31358770, 2019). "As we know that IL-6 has potential tumorigenic ability, positively correlated with the progression of liver cancer, and negatively regulates the body’s immunological function." (PMID 30151798, 2019). "Here, pre-interventional serum concentrations of IL-8 and IL-6 were significantly elevated in patients with liver cancer compared to healthy controls, while serum levels of CCL22 were unaltered between these groups." (PMID 29899223, 2018). "While the role of IL-6 in promoting function in liver cancer is well documented, less is known about leptin signaling in HCC development." (PMID 30224299, 2018). "The sphere formation and migration capacities of liver cancer stem cells showed a similar decrease in response to the treatment with IL6 neutralizing antibody and AZD1480." (PMID 29722127, 2018). "We also further verified that IL6/JAK2/STAT3 signalling functions downstream of the SHH/Gli pathway in liver cancer stem cells." (PMID 29722127, 2018). "Taken together, these results showed that the proliferation, sphere formation and migration capacities of CD90+ liver cancer cells involved activation of IL6/JAK2/STAT3 signalling through the SHH/Gli pathway." (PMID 29722127, 2018). "In line with this, receiver operating characteristic (ROC) curve analyses revealed area under the curve (AUC) values of 0.944 and 0.931 for IL-8 and IL-6 for the discrimination between liver cancer patients and healthy controls." (PMID 29899223, 2018). "Activated fibroblasts further promotes stemness, EMT, chemoresistance, and tumorigenicity of liver cancer cells by IL-6 and IL-8 secretion." (PMID 29335551, 2018). "Application of the JAK2 inhibitor AZD1480 and IL6 neutralizing antibody showed the CD90 and SHH/Gli‐regulated liver cancer stem cell functions were mediated by the IL6/JAK2/STAT3 pathway." (PMID 29722127, 2018). "TM4SF5-positive liver cancer cells show reduced expression of IL6, and TM4SF5 is induced by TGFβ1-mediated signaling." (PMID 29137358, 2017). "In human liver cancer cells, inactivated STAT3 causes the inhibition of IL-6-mediated anti-apoptotic activity." (PMID 27861147, 2017). "Autocrine IL-6 signaling is critical for liver cancer progenitor cell-related disease progression, suggesting future analysis of progenitor cell effects in SMAD7-dependent HCC." (PMID 28134936, 2017). "Constitutive activation of Signal Transducer and Activator of Transcription 3 (STAT3) induced by IL-6 is frequently detected in liver cancer and has emerged as a viable molecular target for liver cancer treatment." (PMID 28430601, 2017). "A higher state of inflammation was observed in liver cancer tissues as evident from upregulation of inflammatory cytokines IL-6 and TNF-α along with NF-κB and STAT3." (PMID 27760163, 2016). "Using a spontaneous tumorigenesis model that closely imitated inflammatory tumors, we found that Mdr2−/−IL6+/+ mice had higher IL-6 levels in tumors and higher rates of early spontaneous liver cancer." (PMID 27589954, 2016). "Nevertheless, our findings corroborate the key observations regarding the role of IL-6 in chronic liver inflammation and hepatocarcinogenesis in murine liver cancer models." (PMID 27489351, 2016).
liver cancer (continued). "IL-6 has a key role in carcinogen-driven liver cancer development, promotes cancer cell proliferation, and inhibits the apoptosis of cancer cells through the activation of STAT3." (PMID 27589954, 2016). "It has therefore been suggested that disruption of IL-6 signaling would abolish the gender disparity in liver cancer at least in the murine DEN model." (PMID 25741592, 2015). "For example, IL-6 and IL-8 were reported to be significantly high expressed and play an important role in migration and sustainable proliferation of human liver cancer cells." (PMID 26606055, 2015). "For practical reasons, we hope that this study will advance our understanding of the role of circulating IL-6 leading to the progression and severity of liver cancer." (PMID 26096712, 2015). "Over-expression of DNMT1 correlates with increased genomic methylation and has been associated with miRNA dysregulation in liver cancer, in which DNMT1 over-expression is induced by IL-6 over-production." (PMID 25705251, 2014). "While IL-6-dependent STAT3 activation is considered a key event in inflammation-induced liver cancer, the anti-inflammation effect of estrogen is well documented." (PMID 24708807, 2014). "In conclusion, the present study has demonstrated that AEG-1 plays a significant role in the proliferation and apoptosis of liver cancer HepG2 cells via downregulated IL-6 secretion and Stat3 activation." (PMID 24348829, 2014). "NNMT promoter activity has also been correlated to the activation of signal transducer and activator of transcription 3 (STAT3) in colorectal tumor tissues and Hep G2 liver cancer cells stimulated with interleukin (IL)-6." (PMID 23990942, 2013). "Our study demonstrates that in vivo monocytes can promote liver cancer cell proliferation via IL-6/STAT3 signaling pathway." (PMID 22136659, 2011). "Constitutively activated IL-6/STAT3 signaling has been detected in a wide variety of human cancers including liver cancer and is considered an important factor for cancer initiation, development, and progression." (PMID 22136659, 2011). "IL-6 levels displayed a positive correlation with irAEs related intestinal toxicity during immunotherapy, IL-6 pathway blockade significantly reduced intestinal damage whereas improved therapeutic outcomes in liver cancer patients." (PMID 40519900, 2025). "Oncologists are aware that CRP and IL-6 values can be elevated in liver cancer." (PMID 40419900, 2025). "IL-6 may promote the chemotherapy resistance and malignant behavior of liver cancer cells by activating the autophagy pathway." (PMID 40919145, 2025). "These cells can secrete interleukin-6 (IL-6), which in turn activates the Notch signaling pathway, enhancing the stem cell-like characteristics of liver cancer cells and promoting the progression of liver cancer." (PMID 41050674, 2025). "Kupffer cells and inflammatory monocytes promote the transition from chronic hepatitis to liver cancer by releasing proinflammatory cytokines such as TNFα, IL-6, and MCP-1, and inducing CD8+ T-cell exhaustion in collaboration with myeloid-derived suppressor cells (MDSCs)." (PMID 39000296, 2024). "Therefore, it seems logical to conclude that IL-6 levels are elevated in patients prone to liver cancer." (PMID 38605023, 2024). "Cardiotrophin-like cytokine factor 1 (CLCF1) is an interleukin-6 (IL-6) family member secreted by cancer-associated fibroblasts (CAFs) that binds to ciliary neurotrophic factor receptor (CNTFR), promoting tumor growth in lung and liver cancer." (PMID 38562778, 2024). "In liver cancer, IL-6 presents a protective role in fibrogenesis." (PMID 38473721, 2024). "Of note, IL6 has been reported to induce TG2 activity in liver cancer." (PMID 38650935, 2024). "When the IL-6 gene was knocked out, it not only reduced the hepatocyte damage caused by the use of DEN in male mice cancer incidence but also eliminated sex differences in liver cancer development in mice." (PMID 38605023, 2024).
liver cancer (continued). "IL-6, a proinflammatory cytokine, plays a crucial role in the pathogenesis of various acute and chronic inflammatory conditions, including liver diseases such as cirrhosis and liver cancer." (PMID 38304429, 2024). "Levels of IL-6, which promotes tumor growth, are increased in liver cancer patients." (PMID 37666817, 2023). "In this set of experiments the three human liver cancer cell lines Hep3B, Huh7 and HepG2 were treated for 24 h with either IL-6 alone (15 ng/mL) or in combination with sIL-6R (100 ng/mL) to simulate classical or IL-6 trans-signaling." (PMID 37108378, 2023). "Therefore, elevated levels of these inflammatory markers (i.e. IL-1β, IL-4, IL-6, IL-10, TNF-α and C-reactive protein) increase the risk of liver cancer development." (PMID 37990536, 2023). "The increased expression of the IL-6 may affect the occurrence of liver cancer through some ways, but its specific process needs further experiments to verify." (PMID 35359408, 2022). "These indicate that regulating IL-6/JAK2/STAT3 signaling pathway may be a therapeutic strategy for liver cancer." (PMID 36591515, 2022). "Therefore, we induced HCC progenitor cell-like spheroid formation by growing Huh7 cells on low-attachment plates and found that IL-6 significantly promoted the malignant progression of liver cancer progenitors." (PMID 36385095, 2022). "Although existing studies have shown somewhat correlation between the occurrence of liver cancer and the level of IL-6, the clinical relationship between the level of IL-6 promoter methylation and HBV-associated HCC has not yet been tested." (PMID 35359408, 2022). "Studies have shown that Icariin, a generic flavonoid compound, inhibits the development and growth of liver cancer by regulating the IL-6/JAK2/STAT3 pathway 11 and also inhibits the expression of PD-L1 by targeting protein IκB kinase α, thus regulating immunity." (PMID 36118529, 2022). "Indeed, studies have shown CAFs as the main source of IL-6, promoting survival, migration, invasion, angiogenesis and stemness in colorectal, gastric, and liver cancer cells." (PMID 35568708, 2022). "Persistent activation of the IL6 signaling pathway is injurious to the liver and might even lead to the development of liver cancer." (PMID 36238273, 2022). "Ni and colleagues found that miR-515-5p could suppress the migration and invasion of liver cancer cells through targeting IL6/JAK/STAT3 pathway." (PMID 36276992, 2022). "Since RIG-I expression is decreased in liver cancer progenitor HcPCs and RIG-I deficiency promotes IL-6-driven hepatocarcinogenesis, we presumed that not only IL-6 was autocrined by HcPCs, but also their response to IL-6 was enhanced." (PMID 36333807, 2022). "DILC has been found to modulate liver cancer stem cells through IL-6/STAT3 axis." (PMID 34991683, 2022). "Notably, upregulation of TIM4 and NF-kB was observed in IL-6 treated liver cancer cells and tumor tissues from patients." (PMID 34657635, 2021). "However, studies have found that the continuous activation of the IL-6 signaling pathway is harmful to the liver, and that IL-6 can promote the occurrence of liver cancer through multiple steps." (PMID 35096574, 2021). "The high levels of CYP2D6 in AS and IL6 in CA suggest variability in liver cancer etiology." (PMID 34597305, 2021). "PHF19 interacted with the components of β-catenin inhibitor in the intercellular substance, inhibiting the decomposition of β-catenin, and promoted the signal transduction of β-catenin/T cells, thereby increasing the level of downstream IL-6 and promoting the movement of liver cancer cells." (PMID 34141488, 2021). "Although these preliminary results require further validation, CYP2D6 and IL6 might have significant clinical impact in the management of liver cancer incidence and application of personalized treatment regimens." (PMID 34597305, 2021). "IL6 is downregulated in AS compared to CA liver cancer patients (log2 FC = -1.72)." (PMID 34597305, 2021).